CD84 (CD84 molecule)
Description:
Self-ligand receptor of the signaling lymphocytic activation molecule (SLAM) family. SLAM receptors triggered by homo- or heterotypic cell-cell interactions are modulating the activation and differentiation of a wide variety of immune cells and thus are involved in the regulation and interconnection of both innate and adaptive immune response. Activities are controlled by presence or absence of small cytoplasmic adapter proteins, SH2D1A/SAP and/or SH2D1B/EAT-2. Can mediate natural killer (NK) cell cytotoxicity dependent on SH2D1A and SH2D1B (By similarity). Increases proliferative responses of activated T-cells and SH2D1A/SAP does not seem be required for this process. Homophilic interactions enhance interferon gamma/IFNG secretion in lymphocytes and induce platelet stimulation via a SH2D1A-dependent pathway. May serve as a marker for hematopoietic progenitor cells Required for a prolonged T-cell:B-cell contact, optimal T follicular helper function, and germinal center formation. In germinal centers involved in maintaining B-cell tolerance and in preventing autoimmunity (By similarity). In mast cells negatively regulates high affinity immunoglobulin epsilon receptor signaling; independent of SH2D1A and SH2D1B but implicating FES and PTPN6/SHP-1. In macrophages enhances LPS-induced MAPK phosphorylation and NF-kappaB activation and modulates LPS-induced cytokine secretion; involving ITSM 2 (By similarity). Positively regulates macroautophagy in primary dendritic cells via stabilization of IRF8; inhibits TRIM21-mediated proteasomal degradation of IRF8.
Synonyms: SLAMF5; hCD84; mCD84; LY9B
Tractability: Antibody: UniProt places it where antibodies can reach, with high confidence; its Gene Ontology location is reachable by antibodies, with high confidence; UniProt predicts a signal peptide or a membrane-spanning region; the Human Protein Atlas places it where antibodies can reach. PROTAC: ubiquitination databases record sites on it; its protein half-life has been measured.
Gene: Protein-coding gene on chromosome 1 (160,541,095 to 160,579,516, reverse strand). Ensembl gene ENSG00000066294.
Subcellular location: Cell membrane
Subcellular location (Human Protein Atlas): Plasma membrane; Vesicles
Pathways (Reactome):
Hemostasis: Cell surface interactions at the vascular wall
Gene Ontology:
Molecular function: identical protein binding; protein binding
Biological process: negative regulation of granulocyte macrophage colony-stimulating factor production; negative regulation of interleukin-18 production; negative regulation of mast cell activation; negative regulation of mast cell degranulation; regulation of store-operated calcium entry; defense response; homophilic cell-cell adhesion; immune response; T cell activation
Cellular component: plasma membrane; external side of plasma membrane; membrane
Genetic constraint (gnomAD): Loss-of-function variants: 21 observed, 33.22 expected, observed/expected ratio (o/e) 0.63, 90% interval 0.45 to 0.91. The upper end of that interval is the gene's LOEUF score, 0.91, which puts it in group 3 of 6, group 1 being the genes least tolerant of losing a copy. Missense variants: 374 observed, 391.82 expected, observed/expected ratio (o/e) 0.95, 90% interval 0.88 to 1.04. Synonymous variants: 141 observed, 144.01 expected, observed/expected ratio (o/e) 0.98, 90% interval 0.85 to 1.13.
Homologues: Orthologues: chimpanzee CD84 (99% identical), macaque CD84 (94% identical), rabbit CD84 (69% identical), pig CD84 (67% identical), dog CD84 (64% identical), mouse Cd84 (59% identical), guinea pig CD84 (56% identical), rat Cd84 (55% identical), zebrafish si:cabz01074946.1 (16% identical). Paralogues in human: SLAMF6 (29% identical), SLAMF7 (28% identical), LY9 (28% identical), SLAMF9 (26% identical), CD244 (21% identical), SLAMF1 (19% identical), CD2 (18% identical), SLAMF8 (17% identical), CD48 (14% identical).
Diseases named in the same sentence as CD84 in open-access papers:
CD84 is named in the same sentence as 51 diseases in open-access papers, as found by Europe PMC text mining. Sharing a sentence is not in itself a finding about the gene and the disease. The quoted sentences say what the papers report.
breast carcinoma (8 papers, 2021 to 2025). "Recent studies have established a gene signature of PMNs and PMN-MDSCs at the single-cell transcriptomes level and identified CD84 as a surface marker for the improved detection and enrichment of MDSCs in breast cancers." (PMID 38385073, 2024). "SLAMF5/CD84 was detected as an identifying marker for myeloid-derived suppressor cells (MDSCs) in breast cancer in a mouse model, and in vitro experiments showed that PBMC-derived human MDSCs upregulate SLAMF5." (PMID 38476238, 2024). "Recently, CD84 was identified as an emerging marker to identify MDSCs in breast cancer." (PMID 40165290, 2025). "One such strategy could be through targeting the marker CD84, where it was shown that MDSCs with increased CD84 expression showed enhanced ROS production and T cell suppression capacity in breast cancer." (PMID 38464388, 2024). "CD84 has been identified as a robust MSDC-specific cell surface marker in breast cancers." (PMID 36788538, 2023). "A recent study identified CD84 and Jaml as possible novel markers for MDSCs in breast cancer." (PMID 34322123, 2021). "In further analysis of the MDSC subpopulations, we evaluated CD84 expression, which characterizes a novel MDSC subpopulation recently identified in breast cancer." (PMID 36045668, 2022). "CD84 is a cell surface receptor of the signaling lymphocytic activation molecule (SLAM) family expressed on some immune cell types and has been identified as a surface marker for improved detection and enrichment of MDSCs in breast cancers." (PMID 36788538, 2023).
chronic lymphocytic leukemia (8 papers, 2018 to 2025). "CD84 promotes tumor cell survival in early chronic lymphocytic leukemia, and inhibition of CD84 leads to cell death." (PMID 36969247, 2023). "Previously, we showed that CD84 bridges between chronic lymphocytic leukemia cells and their microenvironment, and it regulates T cell function." (PMID 33465053, 2021). "Lastly, CD84, a member of the signaling lymphocyte activation molecule (SLAM) family, forms homophilic dimers by self-association and is reported as an important survival receptor in chronic lymphocytic leukemia." (PMID 38609844, 2024). "The recently demonstrated function of CD84 in chronic lymphocytic leukemia cells and their microenvironment may support the potential functional implication of CD84 in lung carcinogenesis." (PMID 33840167, 2021). "Previous studies have shown that CD84 regulates a potentially novel survival pathway in chronic lymphocytic leukemia (CLL)." (PMID 33465053, 2021).
Stroke (8 papers, 2021 to 2024). Sudden impairment of blood flow to a part of the brain due to occlusion or rupture of an artery to the brain. "Clinically, high platelet CD84 expression levels were associated with poor outcomes in stroke patients." (PMID 39416871, 2024). "Clinically, high platelet CD84 expression levels were associated with poor outcome in patients with stroke PLR was inferior to NLR as predictor of outcome and severe neurological complications such as edema in a larger cohort study." (PMID 34685473, 2021). "Furthermore, human arterial blood samples from the ischemic cerebral circulation showed local shedding of SLAMF5, and high expression of CD84 on platelets was associated with poor outcomes in patients with stroke." (PMID 38476238, 2024). "In a clinical study, a high level of platelet CD84 expression resulted in poor outcomes in patients with stroke." (PMID 36968817, 2023). "Recently, CD84, a homophilic cell adhesion molecule could be identified as the mechanistic link between detrimental effects of T-cells and platelets in stroke." (PMID 39582054, 2024). "Remarkably, however, platelet-derived soluble CD84 acts on CD4 + T cell CD84 leading to enhanced CD4 + T cell motility in vitro and aggravated infarct growth following experimental stroke." (PMID 39334369, 2024). "CD84-lacking platelets were shown to reduce cerebral CD4+ T-cell infiltration and thrombotic activity, slowing neurological damage in an experimental model of stroke." (PMID 36968817, 2023).
autoimmune disease (5 papers, 2021 to 2023). A disorder resulting from loss of function or tissue destruction of an organ or multiple organs, arising from humoral or cellular immune responses of the individual to their own tissue constituents. "The effect of the CD84 rs6427528 receptor gene polymorphism on the response of autoimmune diseases to BTs has been studied." (PMID 37240048, 2023). "For example, CD84-mediated signaling induces autoimmune diseases by regulating natural killer cell-mediated cytotoxicity." (PMID 37525657, 2023). "Furthermore, mice lacking PD-1 or PD-L1 spontaneously develop autoimmune diseases, while mice lacking CD84 have been described as grossly indistinguishable from WT mice." (PMID 33465053, 2021).
myeloma (5 papers, 2021 to 2025). "In a myeloma mouse model, it was shown that the activation of CD84 up-regulates PD-L1 expression on MDSCs and thereby suppresses CD8+ T activation and promotes their exhaustion." (PMID 40344054, 2025). "Blocking CD84 induced apoptosis of the myeloma cells, leading to reduced numbers of these malignant cells." (PMID 33465053, 2021). "PD-L1 mRNA and surface protein levels were significantly elevated in CD84-activated BM myeloma cells and stromal cells derived from the patients." (PMID 33465053, 2021). "Strikingly, a significant elevation of CD84 expression was observed on both cell types derived from MM patients compared with its expression on cells derived from the earlier, premalignant stage of smoldering myeloma as well as from healthy BM." (PMID 33465053, 2021). "Targeting CD84 and the CD304-Gal1 axis are other strategies used in myeloma mouse models to restore anti-myeloma T-cell responses by reducing MDSC accumulation and PD-L1 expression." (PMID 36726975, 2022). "In Multiple Myeloma (MM), the expression of CD84 in MM cells was found to be decreased, and these cells could secret Macrophage Migration Inhibitory Factor (MIF), which was able to promote CD84 expression." (PMID 39013845, 2024).
lupus (4 papers, 2017 to 2024). "Previous studies have indicated its involvement in autoimmune and lymphoproliferative disorders, and specific allelic variations in CD84 have been associated with autoimmune disorders, such as systemic lupus erythematosus and rheumatoid arthritis." (PMID 35196822, 2022). "Altogether, these results demonstrated that basophils from SLE patients overexpress PD-L1 and CD84, suggesting that a basophil-TFH cell interaction may occur during lupus pathogenesis." (PMID 38649353, 2024).
rheumatoid arthritis (4 papers, 2013 to 2025). A chronic, systemic autoimmune disorder characterized by inflammation in the synovial membranes and articular surfaces. "Two other studies with 788 and 581 patients with rheumatoid arthritis treated with TNFi could not replicate previous findings of an association with a minor allele in CD84 (rs6427528) and response to TNFi." (PMID 41009564, 2025).
prostate carcinoma (3 papers, 2018 to 2023). A carcinoma that arises from epithelial cells of the prostate gland. "A previous study found that certain substances can prevent or treat prostatic cancer by inhibition of CD84 mRNA, suggesting that further exploration of the role of CD84 in lung cancer may guide the identification of novel therapeutic targets." (PMID 36969247, 2023). "Hence, cross-talk between AHR and inflammation-mediated pathways, but not CD84-mediated pathways, in monocytes but not macrophages may contribute to the modulation of tumor environments by I3C and DIM in prostate cancer." (PMID 29364159, 2018).
breast tumor (2 papers, 2019 to 2024). "Single-cell RNA sequencing studies identified Cd84 mRNA as a novel marker for MDSCs in a murine breast tumor model." (PMID 39338937, 2024).
COVID-19 (2 papers, 2021 to 2026). A disease caused by infection with severe acute respiratory syndrome coronavirus 2. "We found inverse correlations between CD84 with OLAH and IL18R1 levels in our A(H7N9) cohort, and in hospitalised COVID-19 patients across respiratory disease severities." (PMID 41816098, 2026).
lung carcinoma (2 papers, 2023 to 2024). "In this study, we found differential expression of CD84 in lung cancer and normal lung tissue and further uncovered an association of CD84 expression with poor prognosis in multivariate Cox analysis." (PMID 36969247, 2023). "However, the role of CD84 in lung cancer is still not completely understood." (PMID 36969247, 2023).
psoriasis (2 papers, 2022 to 2023). An autoimmune condition characterized by red, well-delineated plaques with silvery scales that are usually on the extensor surfaces and scalp. "CD84 is a known T cell activation marker, genetic variants of which have been associated with response in psoriasis to TNF blockade." (PMID 35958578, 2022).
Anxiety (1 paper, 2017). Intense feelings of nervousness, tension, or panic often arise in response to interpersonal stresses. "Correlation analysis also found the anxiety severity item were positively correlated with CD84 gene expression." (PMID 28333931, 2017). "Additionally, we correlate gene expression profiles with depression and anxiety severity scores and we found that gene CD84 was correlated with HAMD scale in item 10 named as Anxiety psychic (r = 0.318, p = 0.026) in MDD patients." (PMID 28333931, 2017). "The relationship between depression/anxiety severity and genes expression profiles (STRN, CD84 and CTNS) in SSD patients." (PMID 28333931, 2017). "The relationship between depression/anxiety severity and genes expression profiles (STRN, CD84 and CTNS) in MDD patients." (PMID 28333931, 2017).
chronic kidney disease (1 paper, 2024). Impairment of the renal function secondary to chronic kidney damage persisting for three or more months. "CD84 is shown to be highly expressed in patients with chronic kidney disease (KD) with coronary arteritis." (PMID 39858399, 2024).
HCMV infection (1 paper, 2021). "Altogether, we decided on three hit candidate receptors: CD164, which was downregulated from the surfaces of all cells analyzed, and CD84 and CD180, which seem to be myeloid cell-specific receptors with reduced expression upon HCMV infection." (PMID 34399625, 2021).
Hypertension (1 paper, 2024). The presence of chronic increased pressure in the systemic arterial system. "Four proteins (CXCL1, CD84, HO1, and PGF) were linked to disorders of blood pressure, including (early-onset) hypertension." (PMID 38958674, 2024).
Insulin resistance (1 paper, 2020). Increased resistance towards insulin, that is, diminished effectiveness of insulin in reducing blood glucose levels. "Genes with a positive association with inflammation, chemotaxis, insulin resistance, and inflammatory cell death, such as Irf5, Alox5ap, Tlrs, Cd84, Ccr5, Ccl9, and Casp1, were downregulated by EPA." (PMID 32906847, 2020).
leukemia (1 paper, 2025). A malignant (clonal) hematologic disorder, involving hematopoietic stem cells and characterized by the presence of primitive or atypical myeloid or lymphoid cells in the bone marrow and the blood. "Depletion of CD84 altered mitochondrial ultrastructure and function of leukemia cells, and it caused downmodulation of both oxidative phosphorylation and fatty acid oxidation pathways." (PMID 40198133, 2025). "Our findings suggest that CD84 is a critical survival factor regulating metabolic processes in leukemia cells, highlighting its role as a potential therapeutic target for AML." (PMID 40198133, 2025). "In a mechanism study, we observed that CD84 appears to play a pivotal role in maintaining GSH metabolism and NRF2 antioxidant defense in leukemia cells causing ROS accumulation." (PMID 40198133, 2025). "To further elucidate the molecular underpinnings of CD84 in leukemia cells, we induced alterations in the expression of endogenous CD84 and performed RNA-Seq." (PMID 40198133, 2025). "High levels of CD84 expression provided a survival advantage to leukemia cells, whereas CD84 downregulation disrupted their proliferation, clonogenicity, and engraftment capabilities in both human cell lines and patient-derived xenograft cells." (PMID 40198133, 2025). "Collectively, our findings indicate that AML cells depend on CD84 to support antioxidant prosurvival pathways, highlighting a therapeutic vulnerability of leukemia cells." (PMID 40198133, 2025). "Mechanistically, CD84 regulated leukemia cells’ energy metabolism and mitochondrial dynamics." (PMID 40198133, 2025). "CD84 is essential for leukemia cell maintenance in AML mouse models." (PMID 40198133, 2025). "CD84 is a key survival protein for leukemia cells and a potential target to treat AML." (PMID 40198133, 2025).
pancreatic cancer (1 paper, 2023). "Additionally, we analyzed CD84 gene expression using data from the TCGA pancreatic cancer via the Xena platform to evaluate the relationship between myeloid-derived suppressor cells (MDSCs) and the sex of patients with PDA." (PMID 36980700, 2023).
pulmonary TB (1 paper, 2022). "CD84 is more highly expressed in T cells from M. tuberculosis-infected mice than in T cells from uninfected mice and in T cells from pulmonary TB patients than in T cells from healthy donors." (PMID 35196822, 2022). "Transcriptome analysis, quantitative PCR (qPCR), and flow cytometry all indicated that CD84 expression on immune cells was elevated in M. tuberculosis H37Rv-infected mice and in peripheral blood mononuclear cells (PBMCs) from pulmonary TB patients relative to their levels in controls." (PMID 35196822, 2022). "Similarly, PBMCs derived from patients with pulmonary TB displayed higher expression of CD84 than those from healthy donors." (PMID 35196822, 2022). "While the development and function of T and B lymphocytes is not affected by CD84 deficiency in the absence of infection, we show here that CD84 is upregulated in lung tissues from mice infected with M. tuberculosis and in PBMCs from pulmonary TB patients." (PMID 35196822, 2022). "Here, we show that the levels of CD84, a SLAM family receptor, increase in T and B cells in lung tissues from M. tuberculosis-infected C57BL/6 mice and in peripheral blood mononuclear cells (PBMCs) from pulmonary TB patients." (PMID 35196822, 2022).
thrombosis (1 paper, 2014). "To study the effect of CD84 deficiency on arterial thrombus formation in vivo, we subjected mice to a thrombosis model in which the abdominal aorta is mechanically injured and blood flow is monitored with an ultrasonic perivascular Doppler flow probe." (PMID 25551754, 2014).
tuberculosis (1 paper, 2022). A chronic, recurrent infection caused by the bacterium Mycobacterium tuberculosis. "Our results suggest that CD84 has an inhibitory role during M. tuberculosis pathogenesis in mice, making it an attractive target for further investigation in the development of TB-specific immune checkpoint therapies." (PMID 35196822, 2022). "The elevated IFN-γ levels observed here both in M. tuberculosis-infected CD84-deficient mice (at 80 days postinfection) and in CD84− CD4+ T cells from TB patients may be related to the increased levels of Th1 or CD8+ T cell differentiation detected." (PMID 35196822, 2022). "That CD84 is a putative M. tuberculosis infection-specific inhibitory receptor suggests it may be a suitable target for the development of TB-specific checkpoint immunotherapies." (PMID 35196822, 2022).
type 2 diabetes (1 paper, 2022). "Consistent with a proinflammatory state, several key cell surface antigens (Cd4, Cd68, Cd84), immune sensors (Cx3cr1, Clec7a), and macrophage genes (Axl, Slc11a1) were upregulated in hIAPP islets and in type 2 diabetes." (PMID 34554282, 2022).